IL6 (interleukin 6)
Diseases named in the same sentence as IL6 in open-access papers (continued):
Sharing a sentence is not in itself a finding about the gene and the disease.
colitis (continued). "The symbiotic relationship between SP and EcN significantly reduces inflammatory markers such as TNF-α and IL-6, alleviates weight loss and colon shortening symptoms, and preserves intestinal epithelial integrity in a DSS-induced colitis mouse model." (PMID 40563329, 2025). "G. lemaneiformis suppressed TNF-α, IL-1β and IL-6 levels in dextran sulphate sodium (DSS)-induced colitis in Balb/c mice and IEC-6 cells, improving intestinal barrier function and microbiota structure, thus preventing intestinal inflammation." (PMID 40077614, 2025). "Studies have shown that different Lactobacillus strains that possess the hdc gene cluster can reduce colitis through histamine H2 receptor-mediated IL-1β and IL-6 reduction in distal small intestine and cecum of mice (79, –, 81)." (PMID 39902926, 2025). "Mice transplanted with the colitis microbiome showed higher expression of IL-6, IL-1β, and TNF-α in the colon than mice transplanted with the normal mouse microbiome." (PMID 40076732, 2025). "In contrast, hippocampal homogenates revealed increased IL‐2 and IL‐6 cytokine levels following acute colitis." (PMID 40457749, 2025). "Vitamin C has also been shown to prevent DSS-induced colitis by regulating the production of IL-22 and IL-6 in mice." (PMID 40077487, 2025). "Studies have shown that DSS-induced colitis in mice results in increased levels of IL-6 and IL-1β, consistent with the findings of this study." (PMID 40431130, 2025). "Further, dietary administration of S. boulardii to mice with dextran sulfate sodium (DSS)-induced colitis improved colon injury and reduced inflammatory responses by modulating gene expression of proinflammatory cytokines, such as Tnfα, IL-6, and IL-1β." (PMID 40872558, 2025). "In a colitis-induced colon cancer model, triptolide further suppresses IL-6 secretion and reduces the expression of IL-6 receptor (IL-6R), JAK1, and phosphorylated STAT3 proteins." (PMID 40490812, 2025). "In the colitis model, IL‐6 (interleukin‐6) expression was increased, while its antibody showed an inhibitory effect on colitis." (PMID 39803293, 2025). "Administration of S. boulardii in rats with 2,4,6-trinitrobenzenesulfonic acid (TNBS)-induced colitis improved histological damage, diarrhea, and colonic gene expression of IL-1β, IL-6, and Tnfα." (PMID 40872558, 2025). "The study also is the first time to show that the level of IL‐1β, TNF‐α, and IL‐6 in the serum of colitis mice was greatly decreased by IF." (PMID 39898122, 2025). "In this study, TNF-α, IL-1β and IL-6 levels were higher unsupplemented colitis-affected rats compared to healthy rats." (PMID 41515203, 2025). "Analysis of liver tissue from DSS-induced colitis mice revealed elevated production of pro-inflammatory cytokines, such as IL-1β, IL-6, and TNF-α, along with upregulated LPS and MPO levels." (PMID 40725052, 2025). "Findings from previous investigations have shown that the intestinal mucosal barrier was disrupted in rats with experimental colitis when inflammatory factors (such as IL-6, IL-8, IL-1β, and TNF-α) were elevated, leading to intestinal barrier dysfunction." (PMID 40129987, 2025). "At the molecular level, proinflammatory cytokines, including tumor necrosis factor-alpha (TNF-α), interleukin-6 (IL-6), interleukin-1β (IL-1β), and interleukin-17 (IL-17) are key mediators in colitis pathogenesis." (PMID 40572721, 2025). "A significant increase in the production of pro-inflammatory cytokines (e.g., IL-1β, TNF-α, and IL-6) by macrophages was observed in the dextran sodium sulfate (DSS) colitis mouse model." (PMID 40508145, 2025). "Bilophila contributes to the exacerbation of colitis by producing LPS, which induces IL-6 and promotes intestinal barrier damage." (PMID 40243632, 2025). "This consequently suppresses pro-inflammatory cytokines (IL-1β and IL-6), alleviates colitis, and enhances gut barrier function." (PMID 41010521, 2025).
colitis (continued). "When the immune system detects these pathogens, it triggers inflammatory cytokines such as tumor necrosis factor-α (TNF-α), interleukin-6 (IL-6), and nitric oxide, which induce colitis." (PMID 39949663, 2025). "The study in this work demonstrated that supplementation with CW prevents the excessive formation of TNF‐α, IL‐1β, and IL‐6 in the serum of mice with DSS‐induced colitis." (PMID 39830908, 2025). "Both E. coli and E. faecalis exhibited positive correlations with colon TNF-α, IL-6, and IL-17 levels, suggesting their potential role in promoting colitis development." (PMID 41476955, 2025). "In mouse models of colitis, both walnut protein and its enzymatic products effectively suppressed serum IL-1β, IL-6, TNF-α levels, and myeloperoxidase (MPO) activity, thereby preventing colitis progression." (PMID 39203780, 2024). "Results revealed an upregulation of IL-10 expression and a downregulation of IL-1β and IL-6 expression in T. spiralis- infected mice compared to DSS- treated mice alone during the induction of colitis." (PMID 39495798, 2024). "In conclusion, our results showed evidence for the preventive effects of IA-0130 on colitis development via the regulation of IL-6 signaling pathways." (PMID 38916850, 2024). "The leaf methanol extract of M. longifolia, together with its major constituent eucalyptol, have protective effects against acetic acid-induced colitis in rats by significantly reducing the up-relation of serum IL-6 and TNF-α levels." (PMID 38310564, 2024). "In the same way, celastrol administration has been found to relieve the severity of colitis by decreasing IL-1β, IL-6, myeloperoxidase (MPO), RIPK3, and MLKL levels while increasing active caspase-8 levels and E-cadherin." (PMID 39118979, 2024). "Purslane extracts have also been shown to inhibit the levels of pro-inflammatory cytokines (TNF-α, 1L-1β, and IL-6) in mice suffering from dextran sodium sulfate (DSS)-induced colitis." (PMID 39845784, 2024). "In fact, blockade of IL-6 was found to not only ameliorate colitis-irAE but also enhance the antitumor efficacy of anti-CTLA-4 therapy in mouse models and patient cohorts." (PMID 39247203, 2024). "Pro-inflammatory cytokines such as IL-17, IL-1β, IL-6, and TNF-α have been identified as the key driver in colitis-associated inflammation." (PMID 39744127, 2024). "Exposed IS caused colitis in mice, decreasing colon length and IL-10 levels and increasing myeloperoxidase, TNF-α, IL-1β, and IL-6 levels in the colon." (PMID 39519543, 2024). "In the colitis mice, the expression of IL-6, TNF-α, and IL-1β in the colon tissue was significantly increased after treatment with HPAD or HSAD." (PMID 38233383, 2024). "Perilla seed oil, rich in α-linolenic acid, reduces colitis by suppressing inflammatory markers including interleukin-1 (IL-1), interleukin-2 (IL-2), interleukin-4 (IL-4), interleukin-5 (IL-5), interleukin-6 (IL-6), and interleukin-10 (IL-10)." (PMID 39022021, 2024). "It is established that TNF‐α, IL‐6, and IL‐1β are key proinflammatory cytokines involved in the onset of colitis, and IL‐10, an anti‐inflammatory cytokine, increases following Res administration in IBD patients." (PMID 38372468, 2024). "The activation of the IL-6/STAT3 pathway has consistently been identified as a substantial component in colitis." (PMID 38233383, 2024). "Consistently, higher levels of pro‐inflammatory Il1b, Il6, Tnf, Cxcl2 and Cxcl10 mRNA were detected in the colon of Otub2–/– mice, further consolidating the more severe colitis in these mice." (PMID 39358938, 2024). "When compared to control colitis animals, the expressions of inflammatory markers such as IL-1β, IL-4, IL-6, and Cxcl2 were significantly lower in mice receiving IAA treatment." (PMID 39068517, 2024). "Recently, LN successfully lowered pro-inflammatory cytokines IL-6 and NF-κB and attenuated the macroscopic as well as the histological changes in trinitrobenzene sulfonic acid-evoked colitis; an experimental model of IBD in rats." (PMID 37615707, 2024).
colitis (continued). "Butyrate acid and propanoic acid, key components of XYKJP, play a crucial role in reducing colonic mucosal injury and decreasing IL-1β, TNF-α, and IL-6 in the colitis mouse model." (PMID 39133435, 2024). "Compared to the levels in the normal group, the proinflammatory cytokines (e.g., IFN-γ, TNF-α, IL-17A, IL-1β and IL-6) were significantly elevated in the colitis group, suggesting that mice bearing colitis have an increase in proinflammatory cytokines." (PMID 38396052, 2024). "Previous research revealed that BTW alleviates experimental colitis by suppressing the IL-6/STAT3 signaling pathway, modulating the Th17/Treg cell balance, and improving microflora structure and bile acid metabolisms." (PMID 38974042, 2024). "Compared to the control group, the expression levels of the TNF-α (p < 0.001), IL-1β (p < 0.001), and IL-6 (p < 0.05) genes were significantly increased in the DSS-induced colitis group." (PMID 38474831, 2024). "An increasing number of studies show that the development of colitis induces IL-6 overexpression and excessive JAK and STAT phosphorylation in colonic tissues." (PMID 38916850, 2024). "These cytokines play critical roles in the pathogenesis of colitis, with IL-6, TNF-α, and IL-1β promoting immune cell recruitment and tissue damage, while MCP-1 contributes to macrophage activation and mucosal injury." (PMID 39682761, 2024). "In summary, LysM-IL-6OE mice developed signs of systemic inflammation with an IL-6-driven colitis-like phenotype." (PMID 39015379, 2024). "There is growing evidence that the proinflammatory cytokines IL-6 and IL-1β play a crucial part in the uncontrolled colitis process." (PMID 38998493, 2024). "FICZ provides protection against colitis by reducing the production of pro-inflammatory cytokines such as IL-17, IL-1β, IL-6, TNF-α, and IFN-γ, while promoting anti-inflammatory IL-22 production from Th17 cells." (PMID 39767818, 2024). "In parallel, the phosphorylation of NF-κB p65 and IκBα (inhibitor of NF-κB) was decreased following the administration of over-expressed miR-146a EVs, leading to inhibited secretion of TNF-α, IL-6 and IL-1β and thus ameliorated colitis." (PMID 38323035, 2024). "Wild-type mice also had higher expression of genes associated with inflammatory cytokines (Il6 and Il22) and transcription factors downstream of both toll-like receptor and PAR2 signaling (Stat3 and Bcl6), compared to R38E-PAR2 mice after colitis." (PMID 39171684, 2024). "After coculture with HT and LPS for 24 h, HT (100, 200, 400 μM) significantly decreased TNFα and IL6 in the supernatant of LPS-treated cells, which indicated that HT inhibited the inflammation of colitis in vitro." (PMID 39064786, 2024). "Induction of colitis with trinitrobenzenesulfonic acid in IL17R knockout mice demonstrated the involvement of IL17 in preventing weight loss, colonic inflammation, and IL6 production." (PMID 38992956, 2024). "Similar to that in the colonic tissues of acute colitis model mice, IL-6 and TNF-α expression was significantly increased in the colonic tissues of chronic colitis model mice." (PMID 39512421, 2024). "The expression of integrin αvβ6 is correlated to the severity of inflammation, and integrin β6 deficiency significantly reduces the release of pro-inflammatory cytokines, such as TNF-α, interleukin 6 (IL-6) and IL-1β, in intestinal tissues with colitis." (PMID 39015251, 2024). "The levels of the inflammatory factors IL-1β, IL-6, and TNFα in mouse intestinal tissue were studied to evaluate the extent of colitis-related inflammation." (PMID 39250508, 2024). "TNF-α, IL-1b, and IL-6 have been shown to promote colonic inflammation, with TNF-α causing damage to the intestinal mechanical barrier, and IL-10 and IL-12, which are anti-inflammatory cytokines, which can inhibit inflammation." (PMID 39723143, 2024). "Histological lesions and inflammatory cytokine (Il-6, Tnf-α) levels indicate that the colitis model is successfully established." (PMID 38448514, 2024).
colitis (continued). "It has been found that polyphenols from medicinal plants reduce DSS-induced colitis symptoms by decreasing inflammatory cytokines, such as IL-1β and IL-6, together with antioxidant capacity." (PMID 38892549, 2024). "Consistent with the high LPS load in serum, the expression level of inflammatory cytokines TNF-α, IL-1β, and IL-6 significantly increased in the colons of mice with DSS-induced colitis." (PMID 39272608, 2024). "Beta-sitosterol also significantly reduced the colitis pathology score but significantly inhibited the expression of IL-6 and COX-2." (PMID 38324023, 2024). "This study revealed that L. gasseri ATCC33323 can ameliorate physiological damage in mice with colitis, reduce the extent of colitis, decrease inflammatory cell infiltration, and decrease the levels of the inflammatory factors IL-1β, IL-6, and TNFα." (PMID 39250508, 2024). "N. brasiliensis‐derived EVs were used as treatment in a mouse model of chemical‐induced colitis and demonstrated to reduce IL‐6, IL‐1β, IFNγ and IL‐17a and increase IL‐10 expression." (PMID 39113589, 2024). "Apigenin treatment inhibited colon damage, MPO activity, and the production of IL-1β, TNF-α, and IL-6 in DSS-induced colitis, as well as the NF-κB and STAT3 pathways in colitis-associated colon cancer tissues in mice." (PMID 39451206, 2024). "We further measured the production of pro-inflammatory cytokines, TNF-α, IFN-γ, IL-6, IL-1β, and IL-17 in colonic tissue of colitis mice." (PMID 39085655, 2024). "H3K9me2 regulates IL-17 in a murine T cell transfer model of colitis, IL-6 in an inflammatory vascular smooth muscle cell model, Il-8 in an inflammatory intestinal epithelial cell model, and c-FOS in an aged-related impaired memory neuronal cell model." (PMID 39768289, 2024). "Numerous studies have underscored the pivotal role of the IL‐6/STAT3 pathway in the transition from colitis to colon cancer." (PMID 39495702, 2024). "It was also reported that berberine effectively inhibits the activation of the IL-6/STAT3/NF-κB pathway in models of DSS-induced colitis, offering a potential treatment for ulcerative colitis." (PMID 38998031, 2024). "Red cabbage alleviated colitis and intestinal inflammation by decreasing IL6, IL1β, TNFɑ, iNOS, and COX-2 concentrations in DSS mice." (PMID 38779039, 2024). "In a model of obese colitis mice, pectin administration increased the ratio between Bacteroidetes and Firmicutes, reducing the secretion of IL-1β and IL-6, with the attenuation of colitis." (PMID 39061865, 2024). "For example, our previous study showed that the epigenetic modifier Tet2 associates Hdac2 to repress IL-6 during inflammation resolution in myeloid cells, which restrains DSS-induced colitis in mice." (PMID 38346956, 2024). "The reduced severity of colitis in MC-170073-treated mice given DSS was also associated with lower levels of both colonic MPO and the proinflammatory cytokines IL-1β, IL-6, and TNF-α." (PMID 38713616, 2024). "IL-10 is able to suppress T cell-mediated immune response and ameliorate colitis by inhibiting antigen presenting cells, and downregulate IL-1β, IL-6, and TNF-α secreted by macrophages and T cells." (PMID 38397562, 2024). "Meanwhile, the adaptive immune system is not essential for the development of colitis, but the Th1/Th17-cell response, characterized by cytokines such as IFN-γ, IL-6, and IL-17, contributes to the progression of colitis." (PMID 39176394, 2024). "During the inflammatory response caused by colitis-induced model or IBD, IL-1β along with other proinflammatory cytokines such as TNF-α and IL-6 orchestrate the inflammatory response within the lamina propria." (PMID 38323035, 2024). "Se supplementation can decrease the expression levels of main inflammatory cytokines TNF-α, IL-1β, and IL-6 in inflammatory diseases, such as rheumatoid arthritis, atherosclerosis, and colitis." (PMID 38321393, 2024).
colitis (continued). "The inhibition of IL-6 activity by blocking receptors or cytokines with monoclonal antibodies has proved effective in animal models of colitis and in small therapeutic trials for CD." (PMID 38540299, 2024). "DSS-induced colitis was alleviated by Gegen Qinlian decoction, which was mediated by the suppression of IL-6/JAK2/STAT3 signaling." (PMID 39133435, 2024). "Coumaric acid modulated the expression of inflammatory markers, including NF-κB, TNF-α, iNOS, IL-1β, and IL-6, in the colon during acetic acid-induced colitis." (PMID 38732594, 2024). "For example, L-fucose inhibits macrophage M1 polarization, inactivates the NLRP3 inflammasome, and decreases the levels of TNF-α, IL-1β, and IL-6 in mice with DSS-induced colitis." (PMID 38596683, 2024). "Increased IL-6 levels led to the reduced expression of occludin and Cld-5 in the hippocampus and cortex of colitis-afflicted mice." (PMID 38247868, 2024). "We also found an increase in the expression of the inflammatory genes Il6 and Tnfα in Mdr2-deficient mice after DSS colitis, which is in line with our previous study indicating that DSS colitis induces an infiltration of the liver with inflammatory cells." (PMID 38510236, 2024). "Adoptive T cell colitis in PBS-treated mice predictably led to significantly increased expression of IL-6 and TNF mRNA in the colonic mucosa as compared to naïve WT mice or Rag2−/− sham controls." (PMID 39771552, 2024). "Studies conducted on mice with colitis have demonstrated that intact CPP is more efficacious in reducing the expression of pro-inflammatory factors IL-6, CXC motif chemokine ligand 2 (CXCL2), IL-1β, and TNF-α than a single CPP extract." (PMID 39839098, 2024). "In contrast to previous studies, the IL-6 level was significantly higher in the colitis group compared to the control group in our study." (PMID 39105785, 2024). "With regard to IL-6 level in the testes, our findings revealed a notable impact of colitis, as evidenced by the ANOVA results (p < 0.01)." (PMID 39125425, 2024). "In this study, both the HWB and LWB treatments demonstrated a significant reduction in pro-inflammatory factors (TNF-α, IL-6, and IL-1β) in the colon tissues of colitis mice." (PMID 38254526, 2024). "Huangqin Decoction significantly alleviated colitis in mice, reducing body weight loss, disease activity, colon shortening, tissue damage, and levels of TNF-a, IL-6, IL-1β, and COX-2 induced by DSS treatment." (PMID 39411430, 2024). "Cytokine plasma levels currently used to monitor DSS colitis (TNFα, IL6, IL10 and IL17) were dosed at 3 (baseline) and 5.5 months to evaluate systemic inflammation." (PMID 38773640, 2024). "Recent research has increasingly links the signal transducer and activator of transcription-3 (STAT3) pathway to IBD, with the IL-6/STAT3 signaling pathway consistently recognized as a noteworthy factor in colitis development." (PMID 38233383, 2024). "In mouse models of enterocolitis and colitis, IL-23-activated Th17 cells were found to produce significant amounts of IL-17 and IL-6, indicating a synergistic action of these cytokines in the inflammatory process." (PMID 39195452, 2024). "A significant decrease in mRNA expression of colon TNF-alpha, IL-1, and IL-6 was dominantly observed in dextran sulfate sodium-induced colitis in mice with a gamma-oryzanol diet (100 mg/kg body weight/day for 18 days) when compared with a normal food diet." (PMID 38337717, 2024). "Taken together, these results indicated that IA-0130 attenuated DSS-induced mouse colitis by regulating the IL-6 signaling pathway in inflamed colonic tissues." (PMID 38916850, 2024). "To further elucidate the anti-inflammatory effects of HU308 in DSS-induced colitis, we measured the levels of several pro-inflammatory cytokines in chronic colon tissues, including IL-6, IL-1β, IL-17, MCP-1, TNF-α, and IFN-γ." (PMID 39682761, 2024).